RASA3 (RAS p21 protein activator 3)
Description:
Inhibitory regulator of the Ras-cyclic AMP pathway. Binds inositol tetrakisphosphate (IP4) with high affinity. Might be a specific IP4 receptor.
Synonyms: GAP1IP4BP; GAPIII
Tractability: Antibody: UniProt places it where antibodies can reach, with medium confidence; its Gene Ontology location is reachable by antibodies, with medium confidence. PROTAC: ubiquitination databases record sites on it; its protein half-life has been measured.
Gene: Protein-coding gene on chromosome 13 (113,977,783 to 114,132,775, reverse strand). Ensembl gene ENSG00000185989.
Subcellular location: Cell membrane
Pathways (Reactome):
Signal Transduction: Regulation of RAS by GAPs
Gene Ontology:
Molecular function: calcium channel regulator activity; GTPase activator activity
Biological process: platelet activation; regulation of intracellular signal transduction; signal transduction; intracellular signal transduction; negative regulation of Ras protein signal transduction; response to stress
Cellular component: cytoplasmic side of plasma membrane; cytosol; plasma membrane
Genetic constraint (gnomAD): Loss-of-function variants: 66 observed, 99.65 expected, observed/expected ratio (o/e) 0.66, 90% interval 0.54 to 0.81. The upper end of that interval is the gene's LOEUF score, 0.81, which puts it in group 3 of 6, group 1 being the genes least tolerant of losing a copy. Missense variants: 971 observed, 1,111.4 expected, observed/expected ratio (o/e) 0.87, 90% interval 0.83 to 0.92. Synonymous variants: 500 observed, 453.2 expected, observed/expected ratio (o/e) 1.1, 90% interval 1.02 to 1.19.
Homologues: Orthologues: mouse Rasa3 (95% identical), dog RASA3 (95% identical), macaque RASA3 (94% identical), guinea pig RASA3 (94% identical), pig RASA3 (94% identical), rat Rasa3 (93% identical), tropical clawed frog rasa3 (89% identical), chimpanzee RASA3 (83% identical), zebrafish rasa3 (83% identical), Drosophila melanogaster RasGAP1 (42% identical), Drosophila melanogaster raskol (20% identical), Caenorhabditis elegans gap-1 (18% identical), and 1 more. Paralogues in human: RASA2 (60% identical), RASAL1 (31% identical), RASA4 (30% identical), RASA4B (30% identical), NF1 (27% identical), RASAL2 (22% identical), DAB2IP (21% identical), RASA1 (18% identical), RASAL3 (16% identical).
Diseases named in the same sentence as RASA3 in open-access papers:
RASA3 is named in the same sentence as 30 diseases in open-access papers, as found by Europe PMC text mining. Sharing a sentence is not in itself a finding about the gene and the disease. The quoted sentences say what the papers report.
Thrombocytopenia (7 papers, 2014 to 2022). A reduction in the number of circulating thrombocytes. "Ex vivo studies in mice expressing a catalytically inactive Rasa3 variant (Rasa3ΔGAP) or a point mutant (G125V) focused on defective MK function as the cause of the observed thrombocytopenia." (PMID 35290242, 2022). "RASA3 (RAS P21 protein activator 3) is a Ras-GTPase activating protein that causes anemia and thrombocytopenia in mice when mutated." (PMID 34262470, 2021). "We and others reported that loss-of-function of Rasa3 was associated with a severe thrombocytopenia, providing a possible explanation for the embryonic hemorrhages and lethality." (PMID 29381707, 2018). "Mice homozygous for the scat (severe combined anemia and thrombocytopenia) mutation in the Rasa3 gene exhibit successive episodes of severe bleeding associated with embryonic and postnatal mortality." (PMID 29381707, 2018). "One such spontaneous model is the autosomal recessive scat (severe combined anemia and thrombocytopenia) mouse model; scat carries a missense mutation in the protein-coding Rasa3 gene." (PMID 29922180, 2018). "A spontaneous G125V mutation of Rasa3 was found in scat (severe combined anemia and thrombocytopenia) mice, which undergo hematological “crises,” whereby blood cells are depleted and take on a diseased morphology, also causing eventual lethality." (PMID 27903653, 2017). "Here, we show that Rasa3 catalytic inactivation in mouse hematopoietic cells results in a lethal syndrome characterized by severe defects during megakaryopoiesis, thrombocytopenia and a predisposition to develop preleukemia." (PMID 24967784, 2014). "Collectively, our results indicate that the loss of Rasa3 catalytic activity in 20/24 SCID-Rasa3−/− mice leads to megakaryocyte alterations, to thrombocytopenia, hemorrages and a regenerative anemia." (PMID 24967784, 2014). "A major role for RASA3 in hematopoiesis was first identified upon positional cloning of the co-isogenic autosomal recessive mouse mutation, scat (severe combined anemia and thrombocytopenia)." (PMID 33370780, 2020). "Furthermore megakaryocytic conditional Rasa3 knock-out mice were also severely thrombocytopenic, and mice with a H794L mutation in Rasa3 showed a drastic reduction in Rasa3 expression and thrombocytopenia." (PMID 27903653, 2017). "Concomitant loss of CalDAG-GEFI (Cdg1–/–) normalized both platelet count and platelet life span in R3hlb/hlb mice, suggesting that unrestrained Rap1 activation leading to enhanced platelet clearance is the main reason for thrombocytopenia in Rasa3-mutant mice." (PMID 35290242, 2022). "A key conclusion of this work is that increased platelet clearance is the main reason for thrombocytopenia in Rasa3-mutant mice." (PMID 35290242, 2022). "Thrombocytopenia in Rasa3-mutant mice was assigned to both increased platelet clearance and impaired platelet production." (PMID 35290242, 2022). "B6NJ Mx1-Cre; Rasa3 null mice display severe anemia, thrombocytopenia and leukopenia, closely mirroring the B6;129 Mx1-Cre; Rasa3 null phenotype." (PMID 33370780, 2020). "We and others have shown that mice expressing inactive mutants of Rasa3 die during mid-embryonic life and display hemorrhages and severe thrombocytopenia resulting from developmental defects during megakaryopoiesis." (PMID 29381707, 2018). "Research into establishing the role of Rasa3 in platelet function has been hindered by embryonic lethality of the global Rasa3 knock-out mice and severe thrombocytopenia of animal models with impaired Rasa3 expression." (PMID 27903653, 2017). "By contrast, Rasa3 inactivation specifically in megakaryocytes caused a severe thrombocytopenia but no embryonic lethality." (PMID 29381707, 2018). "Despite marked morphological and ultrastructural abnormalities, megakaryocytes in hypomorphic Rasa3hlb/hlb (R3hlb/hlb) or Rasa3–/– mice demonstrated robust proplatelet formation in vivo, suggesting that defective thrombopoiesis is not the main cause of thrombocytopenia." (PMID 35290242, 2022).
Thrombocytopenia (continued). "In conclusion, our results demonstrate that mice with a catalytic inactivation of Rasa3 protein in the hematopoietic system develop a lethal syndrome characterized by defects during megakaryocyte development and differentiation, and leading to a severe thrombocytopenia." (PMID 24967784, 2014). "Similar observations were made in R3–/– Cdg1+/– mice completely lacking Rasa3 expression, which also exhibit severe thrombocytopenia and a marked reduction in platelet life span." (PMID 35290242, 2022). "Studies in the scat mutant mouse model, characterized by severe anemia, thrombocytopenia and leukopenia, and confirmed in zebrafish by morpholino knockdown, firmly established a critical non-redundant role of RASA3 in vertebrate blood formation." (PMID 33370780, 2020). "We furthermore show that two Rasa3 mutants (H794L and G125V), which are expressed in different mouse models of thrombocytopenia, lack both Ras and Rap1GAP activity and do not affect integrin αIIbβ3-mediated spreading of CHO cells on fibrinogen." (PMID 27903653, 2017).
anemia (5 papers, 2014 to 2021). A reduction in the number of red blood cells, the amount of hemoglobin, and/or the volume of packed red blood cells. "In this study, we elucidate mechanisms contributing to anemia in scat mice during crisis events and propose a model in which loss of RASA3 function during erythropoiesis leads to dysregulation of several key cellular processes with the final result of anemia." (PMID 29922180, 2018). "In Mx1-Cre; Rasa3 mutant mice, stress erythropoiesis is established within two weeks of induction of anemia; the spleen is grossly enlarged and its normal nodular architecture is effaced by expansion of the red pulp." (PMID 33370780, 2020).
acute myeloid leukemia (3 papers, 2014 to 2020). Acute myeloid leukemia (AML) is a group of neoplasms arising from precursor cells committed to the myeloid cell-line differentiation. "Furthermore, the recurrent deletion of chromosome 13, which includes the RASA3 gene, in Burkitt and T-cell lymphomas and in acute myeloid leukemia (AML) suggests a potential role of RASA3 in these blood tumors." (PMID 33096593, 2020).
bone marrow failure (2 papers, 2018 to 2020). "Despite the dramatic phenotype leading to bone marrow failure in scat, so far there has been no report of human patients with a mutation in RASA3 leading to similar conditions." (PMID 33370780, 2020).
hepatocellular carcinoma (2 papers, 2020 to 2021). A malignant tumor that arises from hepatocytes. "Recently, RASA3 hypomethylation has been identified as a potential mechanism for hepatocellular carcinoma development, and therefore, as a useful biomarker for early detection." (PMID 34680511, 2021). "RASA3 hypomethylation is a frequent characteristic of hepatocellular carcinoma, and serves as a potential biomarker in early detection." (PMID 33036415, 2020).
autoimmune disease (1 paper, 2023). A disorder resulting from loss of function or tissue destruction of an organ or multiple organs, arising from humoral or cellular immune responses of the individual to their own tissue constituents. "Blocking RASA3 might modulate LFA-1 function and T-cell activity in autoimmune diseases." (PMID 37190045, 2023).
bladder tumor (1 paper, 2021). "RAS P21 Protein Activator (RASA3) has been determined to be a novel tumor suppressor with low expression in colorectal and bladder tumor." (PMID 34540825, 2021).
bone marrow failure syndrome (1 paper, 2020). "Much future work will be required in order to fully characterize the specific mechanisms by which RASA3 regulates all aspects of mammalian hematopoiesis, including erythroid differentiation, to identify a potential new targetable axis in bone marrow failure syndromes." (PMID 33370780, 2020). "After characterizing the role of RASA3 in murine erythropoiesis, we next investigated the potential role of RASA3 in human erythropoiesis to confirm the relevance of the RASA3-Ras axis to inherited bone marrow failure syndromes." (PMID 33370780, 2020).
breast carcinoma (1 paper, 2022). "Moreover, we provide a proof of concept that inhibiting PI3KC2α or targeting RASA3 activity can block the metastatic spreading of breast cancer cells overexpressing PI3KC2α in vivo." (PMID 35098698, 2022). "Proof‐of‐concept is eventually provided that inhibiting PI3KC2α or lowering RASA3 activity at focal adhesions significantly reduces the metastatic burden in PI3KC2α‐overexpressing breast cancer, thereby suggesting a novel strategy for anti‐breast cancer therapy." (PMID 35098698, 2022). "Finally, our data indicate that reduction in RASA3 activity is sufficient to prevent metastasis in both cellular and animal models of breast cancer." (PMID 35098698, 2022). "On the other, GAPs like RASA3 are potentially druggable and our proof‐of‐concept study provides evidence that inhibition of RASA3 GAP activity can significantly reduce metastasis of breast cancer irrespective of the subtype and likely even in other cancer types." (PMID 35098698, 2022).
Cognitive impairment (1 paper, 2025). Abnormal cognition is characterized by deficits in thinking, reasoning, or remembering. "FCGR2A‐mediated phagocytosis of synaptic components by microglia could contribute to cognitive impairment, while RASA3's role in endothelial barrier integrity may influence blood‐brain barrier disruption in SLE encephalopathy." (PMID 40958401, 2025).
gastric cancer (1 paper, 2021). A primary or metastatic malignant neoplasm involving the stomach. "Furthermore, several genes belonging to the Ras GTPase-activating protein (RasGAP) family, including RASA3 (P = 0.0005), RASA4 (P = 0.003), and RASAL3 (P = 0.0016), were identified with hypermethylated promotors in EBVaGCs compared with that in precursor lesions and other gastric cancers." (PMID 34493320, 2021).
leukopenia (1 paper, 2020). "Western blotting confirmed loss of RASA3 protein in Mx1-Cre; Rasa3 mutant red cell membranes within 2 weeks of the final Poly(I:C) injection at which time the mice are profoundly anemic and thrombocytopenic with significant leukopenia." (PMID 33370780, 2020).
Macrothrombocytopenia (1 paper, 2022). "Here we used various mouse models and approaches to demonstrate that macrothrombocytopenia associated with Rasa3 deficiency is predominantly caused by integrin-mediated platelet clearance." (PMID 35290242, 2022). "Here, we investigated the mechanism by which deficiency in Rasa3, a critical negative regulator of Rap1, causes macrothrombocytopenia in mice." (PMID 35290242, 2022). "In this study, we aimed to definitively determine whether the severe macrothrombocytopenia in Rasa3-mutant mice is predominantly the result of defective platelet production or impaired platelet survival and how Rasa3-mutant platelets are prematurely cleared from circulation." (PMID 35290242, 2022).
multiple sclerosis (1 paper, 2021). A progressive autoimmune disorder affecting the central nervous system resulting in demyelination. "Differential methylation of both NTN1 and RASA3 has been reported in blood mononuclear cells of patients affected by the neurodegenerative disease, multiple sclerosis (MS), a disease known to be influenced by high body temperature." (PMID 34122501, 2021).
Pancytopenia (1 paper, 2020). An abnormal reduction in numbers of all blood cell types (red blood cells, white blood cells, and platelets). "In adults, bone marrow blood cell production and spleen stress erythropoiesis are suppressed significantly upon induction of RASA3 deficiency, leading to pancytopenia and death within two weeks." (PMID 33370780, 2020). "Moreover, in keeping with reduced progenitors including megakaryocyte-erythroid progenitors (MEPs), the functional capacity of mutant bone marrow to produce BFU-E and CFU-E colonies in vitro is strikingly reduced, all of which would be predicted to contribute to pancytopenia in the absence of RASA3." (PMID 33370780, 2020).
preleukemia (1 paper, 2014). "The exact mechanism of this preleukemia was not defined in this work, but active GTP-bound Ras level was similar in Rasa3+/+ and Rasa3−/− fetal liver CD117+ hematopoietic stem cells." (PMID 24967784, 2014).
pulmonary arterial hypertension (1 paper, 2024). Pulmonary arterial hypertension (PAH) is a group of diseases characterized by mean pulmonary artery pressure >20 mmHg and elevated pulmonary arterial resistance leading to right heart failure. "The recent identification of the RASA3 gene as a candidate gene involved in the pathogenesis and prognosis of PH in SCD, as well as pulmonary arterial hypertension in non-SCD patients, is also an important finding." (PMID 38732015, 2024).
tumor (7 papers, 2014 to 2025). "RASA3 is poorly expressed in hepatocellar carcinoma in association with promoter hypomethylation, which is associated with the clinical features of tumor patients." (PMID 34752201, 2021). "Prior studies have linked several genes (LGALS8, PTPN12, YTHDC2, APOBEC3G, GPX3, RASA3, and TSPAN4) to immune responses, highlighting the impact of the tumor microenvironment (TME) on DCIS." (PMID 41020869, 2025).
cancer (4 papers, 2021 to 2024). A tumor composed of atypical neoplastic, often pleomorphic cells that invade other tissues. "Indeed, some cancer associate isoforms such as ALK and RASA3 were shown to play a role in cancer progression while other cancer-specific isoforms such as ERBB2 were found to have a better prognostic value then canonical ERBB2 expression." (PMID 33499898, 2021). "In the Cancer Genome Atlas (TCGA) test dataset, eight genes were detected, and six of them were survival associated (DPP4, FFAR4, RASA3, RASGRF1, XCR1, and STX11)." (PMID 34760708, 2021).
RASA3 also shares sentences with these, for which no sentence is quoted: leukemia (2 papers); aneurysm (1); arterial hypertension (1); atherosclerosis (1); Autoimmunity (1); blood tumors (1); glioma (1); neurodegenerative disease (1); Obesity (1); Splenomegaly (1); T-cell lymphomas (1).